CASP1 (caspase 1)
Diseases named in the same sentence as CASP1 in open-access papers (continued):
Sharing a sentence is not in itself a finding about the gene and the disease.
Sepsis (continued). "Firstly, we found that CD14+ monocytes from pneumonia-induced sepsis patients had considerably greater levels of the proteins TLR4, NLRP3, ASC1, cleaved caspase-1, IL-1, and GSDMD in contrast to pneumonia patients without sepsis and healthy people." (PMID 36923408, 2023). "Here, we demonstrate that the lack of caspase-1/11 affects the expression of the different gasdermins in specific tissues during sepsis, indicating that tissue damage and subsequent organ dysfunction during sepsis could be mediated by the activation of several gasdermins." (PMID 34996441, 2022). "The canonical and non-canonical inflammasome activation leads to caspase-1 and caspase-4/5/11 activation respectively, with subsequent GSDMD processing as a key regulator mechanism of inflammation during sepsis." (PMID 34996441, 2022). "Furthermore, caspase-11-knockout mice, rather than caspase-1-knockout mice, can reduce neutrophil NET release and protect against CLP-induced sepsis." (PMID 36059483, 2022).
colitis (157 papers, 2013 to 2026). Inflammation of the colon. "Concordantly, loss of Nlrp3, Asc or caspase-1 led to severe colitis but also to colitis-associated CRC (CAC)." (PMID 35517498, 2022). "Considering that caspase-1 was downregulated in the colitis-associated cancer mouse model and caspase-1 plays a central role in cell pyroptosis, we explored cell death by TEM." (PMID 35281860, 2022). "Using this model, a series of studies reported that inflammasome components are essential for protecting mice from colitis-associated colon cancer by also using NLRP or caspase-1-deficient mice." (PMID 34571825, 2021). "Nlrp3- and Caspase 1-deficient mice were reported to show ameliorated colitis severity, while others reported that DSS-induced colitis was aggravated in these mice." (PMID 34721422, 2021). "In contrast, other studies have found that mice with NLRP3, ASC, or caspase-1 deficiency exhibited more severe experimental colitis and decreased intestinal epithelial integrity, suggesting a protective role of the NLRP3 inflammasome." (PMID 34322027, 2021). "Caspase-1 deficiency has been demonstrated to enhance tumor development in an AOM/DSS-induced colitis-associated colorectal cancer model through the regulation of colonic epithelial cell proliferation and apoptosis that is usually mediated by NLRC4 activity." (PMID 34571825, 2021). "By contrast, another study showed that caspase-1 KO mice had increased susceptibility to DSS-induced colitis, and the severity of colitis was associated with a decrease in IL-18 production." (PMID 33143375, 2020). "For instance, Nlrp3-/-, Asc-/-, and caspase-1-/- mice were observed to be highly susceptible to DSS-induced colitis." (PMID 33119702, 2020). "A series of studies using various NLRP or caspase-1-deficient mice have reported that inflammasome activities protect mice from colitis-associated colon cancer (CAC) induced by azoxymethane/dextran sodium sulfate (AOM/DSS)." (PMID 28955343, 2017). "Down-regulation of CASP1 was found in human colon cancer and enhanced tumor formation in a colitis-associated colorectal cancer model." (PMID 28388569, 2017). "There is similar controversy regarding the role of the inflammasome in mouse models of IBD, with some studies demonstrating that deficiency of NLRP3 or caspase 1 reduced the severity of colitis while others showed the opposite effect." (PMID 27505062, 2016). "In a previous study using DSS-induced model of colitis, mice deficient in IL-1β-converting enzyme (caspase-1) exhibited attenuated signs of intestinal inflammation, suggesting the therapeutic relevance of IL-1 family blockade." (PMID 27293323, 2016). "ASC and caspase-1 are found in many tissues and cell types and have been shown to protect against colitis-associated CRC in mice." (PMID 26378020, 2015). "Several studies showed that mice deficient for inflammasome components including NLRP3, ASC, and caspase-1 were highly susceptible to acute colitis induced by DSS, indicating the protective role of inflammasome in acute colitis." (PMID 25120559, 2014). "Mice deficient in the inflammasome components ASC and caspase-1 are susceptible to DSS colitis and display heightened intestinal permeability and commensal bacterial translocation probably due to an impaired epithelial restitution and proliferation." (PMID 24886810, 2014). "Caspase-1/Caspase-11-deficient mice were found to be hypersusceptible for C. rodentium infection, as determined by increased intestinal bacterial loads, colitis, and hyperplasia." (PMID 24381573, 2013). "Mice deficient in caspase-1 experience increased disease severity when subjected to DSS colitis and that administration of exogenous IL-18 restored mucosal healing in these mice." (PMID 24115947, 2013). "NLRC4 along with caspase-1 has been shown to regulate tumorigenesis in a mouse model of colitis-associated colorectal cancer (CAC)." (PMID 24273542, 2013).
colitis (continued). "For example, the caspase-1-deficient mouse is resistant to colitis but the IL-1β-deficient mouse is susceptible in the same disease model." (PMID 24115947, 2013). "Nlrp3, Asc and Caspase-1/11 KO mice are also hyper-sensitive to acute DSS colitis, with low colonic IL-18 levels associated with disease susceptibility, while administration of exogenous IL-18 ameliorates colitis severity." (PMID 23847622, 2013). "In particular, leucine-rich-repeat-containing Nlrp3−/− mice show an increase in acute and recurring colitis and colitis-associated cancer, although the disease outcome is less severe in Nlrp3−/− mice than in Pycard−/− or Casp1−/− animals." (PMID 23847622, 2013). "Additionally, there is evidence that Schisandrin B reduces Colonic tissue pro-Caspase-1 and expression and Gasdermin D protein levels by regulating pyroptosis, which in turn alleviates the loss of epithelial cells in colitis." (PMID 40582769, 2025). "However, other studies have shown that Caspase-1-/-/Caspase-11-/- mice become susceptible to colitis, which suggests a protective effect of pyroptosis against colitis." (PMID 34828992, 2021). "Of note, mice deficient in caspase-1 displayed a hypoproliferative intestinal epithelium, while mice deficient in the intrinsic caspase-1 inhibitor, caspase-12, displayed exacerbated colitis-associated colorectal carcinogenesis due to increased IEC proliferation." (PMID 33102234, 2020). "However, sinapic acid treatment also decreased the serum and colonic levels of IL-1β and IL-18, which were associated with decreased NLRP3, ASC, and caspase-1 protein levels in the colons of colitis mice." (PMID 33312339, 2020). "Recently, it was shown that the NLRP3 inflammasome, which is a complex that contains NLRP3, ASC, and caspase-1, plays an important role in colitis and colitis-associated colon cancer (CAC) and is also known as a potential target for the prevention of colitis and CAC." (PMID 33312339, 2020). "Caspase-1 deficiency resulted in enhanced tumor formation in the azoxymethane and dextran sodium sulfate colitis-associated colorectal cancer mouse model through the regulation of colonic epithelial cell proliferation and apoptosis, but not through the regulation of inflammatory cells." (PMID 31439870, 2019). "Indeed, NLRP3 inflammasome-deficient mice, including NLRP3−/−, ASC−/− and Caspase-1−/− mice, were increased highly susceptible to colitis-associated colorectal tumor formation." (PMID 30696442, 2019). "In addition, caspase-1−/− animals were more susceptible to DSS-mediated colitis, which was associated with decreased epithelial cell proliferation and IL-18 secretion." (PMID 28979266, 2017). "NLRP3 as well as caspase-1-deficient mice were protected from DSS-induced colitis." (PMID 27965665, 2016). "Although it remains unclear why caspase-1 deficiency worsens DSS colitis, in humans with Crohn’s disease, natalizumab, the antibody that blocks the very late antigen-4 (VLA-4), is highly effective in treating the disease." (PMID 24115947, 2013). "In addition, ASC and caspase-1 knockout mice are also susceptible to DSS-induced colitis and colitis-associated colon cancer, suggesting that the activation of the NLRP3 inflammasome may have an inhibitory effect on colorectal carcinogenesis." (PMID 37497237, 2023). "This pathway and associated inflammatory markers could be relevant in colitis as NLRP3 inflammasome activity (critical for caspase 1-dependent release of IL-1β and IL-18) in the CNS has been implicated in the exacerbation of neuroinflammation by DSS-induced colitis in aging mice." (PMID 34983592, 2022). "This hypothesis was proven true by administering mice MCC950, a specific inhibitor of the NLRP3 inflammasome, as MCC950 administration reduced the severity of colitis in Slco2a1-deficient mice via suppressing the expression of mature IL-1β and cleaved caspase-1." (PMID 32184453, 2020).
colitis (continued). "However, a conundrum has developed whether caspase-1 deficiency is protective or detrimental in DSS colitis." (PMID 24115947, 2013). "Therefore, we hypothesized that binding of TXNIP to NLRP3 activates the inflammasome, which causes autocleavage of caspase-1 and the release of mature cytokines IL-1 beta and IL-18 during colitis." (PMID 23915129, 2013). "In future work, we plan to establish animal models of colitis, depression, and their comorbidity, and to examine tissue-specific expression changes of key targets such as CASP1 using qPCR and Western blot analyses." (PMID 41595424, 2025). "In DSS-induced mouse colitis models, inhibition of mRNA expression of caspase-1 or IL-1β gene can alleviate colitis." (PMID 40362256, 2025). "Preclinical studies have demonstrated that VX-765 administration effectively reduces IL-1β secretion and attenuates inflammation in models of inflammatory diseases and alleviates DSS-induced colitis in mice by suppressing caspase-1 mediated pyroptosis." (PMID 40869366, 2025). "Our current findings demonstrate that A. cristatum treatment substantially diminishes the expression of key NLRP3 inflammasome components including NLRP3, ASC, and Caspase-1 in a model of DSS-induced colitis." (PMID 40001993, 2025). "Further, the NLRP3-mediated inflammasome activity was inhibited based on results showed that DCA was able to reduce expression level of cleaved caspase-1 and inhibit the activation of IL-1β in colitis-induced mouse model." (PMID 37902927, 2024). "An intriguing finding of our study is the discovery of IL-1β and caspase-1 activation by DSS-induced colitis, which accounts for pyroptosis." (PMID 38491049, 2024). "Inflammatory cytokines and expression of M1 polarization markers, p47phox, NLRP3, Caspase-1 p20 were also increased in macrophages isolated from TNBS-induced colitis mice." (PMID 38796413, 2024). "To confirm pyroptosis in a single cycle of DSS-induced colitis, we further examined the protein markers for pyroptosis (i.e., IL-1β and caspase-1), and found the expected changes in IL-1β and caspase-1 levels." (PMID 38491049, 2024). "Another Caspase-1-specific inhibitor, namely Ac-YVAD-cmk, suppressed intestinal inflammation and reduced the severity of colitis in Il10-deficient mice." (PMID 39684769, 2024). "Cardamonin and DMF, having anti-inflammatory and antioxidant effects, improved colitis in a DSS-induced colitis mouse model through activation of the Nrf2 pathway, thus reducing the activation of caspase-1 and the release of effector molecules." (PMID 39684769, 2024). "To test the distinct impacts of disulfiram and DMF on GSDMD processing in vivo, we collected IECs from the colon after DSS colitis induction and analyzed the caspase-1 cleavage and GSDMD cleavage by Western blotting." (PMID 38607004, 2024). "On the contrary, the study conducted by Siegmund and co-workers reported that a caspase-1 deficit in DSS-induced colitis mice had protective effects on the evolution of the disease, related to the limited production of IL-1β and IL-18." (PMID 39684769, 2024). "In this study, inflammasome-associated factors, including p-STAT3, NLRP3, IL-1β, and caspase-1, were significantly enhanced in a DSS-induced mouse colitis model." (PMID 39329121, 2024). "DCA significantly reduced the level of cleaved caspase-1 by 50% in oxazolone-induced colitis, indicating effective reversal of caspase-1 activation in colitis through reducing NLRP3 protein level." (PMID 37902927, 2024). "Based on that, we measured if DCA-induced reduction in the expression level of NLRP3 would reduce the level of cleaved caspase-1 and hence IL-1β level in oxazolone-induced colitis as measured by Western Blot." (PMID 37902927, 2024). "Increased NFκB and decreased IL18 expression also contributed to the progression of colitis and CAC tumorigenesis in Casp-1- and Casp-12-deficient animals." (PMID 38892354, 2024).
colitis (continued). "Taken together, these results highlight that the protective effect of ruscogenin on DSS-induced colitis was associated with the attenuation of NLRP3 inflammasome activation and caspase-1-dependent pyroptosis by inhibiting the TLR4/NF-κB pathway." (PMID 38790951, 2024). "Apigenin (API) is a flavone (4,5,7-trihydroxyflavone) that is ubiquitously distributed in plants and has shown the ability to prevent DSS-induced colitis via regulating CASP1’s activity to inhibit the activation of the NLRP3 inflammasome in the colon." (PMID 37833958, 2023). "In our previous study, we found that QCS ameliorated DSS-induced colitis by inhibiting the expression of Caspase-1 and IL-1β during inflammasome activation." (PMID 36762118, 2023). "For example, caspase-3, -7, and -12, and the cleaved forms of caspase-1, -12, and -7 significantly increased post-colitis induction." (PMID 38034999, 2023). "DSS-induced mice treated with Sinapic acid had significantly decreased levels of NLRP3, IL-1b, ASC, and Caspase-1, which improved symptoms of colitis.." (PMID 37849728, 2023). "Although activated caspase-1 is crucial for DSS-induced inflammation, caspase-1- or NLRP3-deficient mice developed significantly less severe colitis than wild-type mice." (PMID 37240022, 2023). "Caspase-1 inhibitor VX765 restrains pyroptosis by restraining caspase-1/GSDMD pathway to alleviate colitis in mice, indicating a dose-dependent therapeutic effect on APS." (PMID 37063905, 2023). "Pyroptosis has recently been verified as a critical cell death pathway in colitis, and caspase-1/GSDMD-mediated pyroptosis is an inflammatory cell death process that has become a novel target for UC treatment." (PMID 37580819, 2023). "NLRP6 expression in intestinal epithelial cells protects against colorectal cancer and colitis via a mechanism dependent on caspase-1 mediated IL-18 production." (PMID 36761775, 2023). "Taken together, SIT did ameliorate experimental colitis by inhibiting the NLRP3/Caspase-1/GSDMD-dependent pyroptosis pathway." (PMID 37954856, 2023). "Aberrant NLRP3 inflammasome activation involves the participation of varied components including ASC and Caspase-1 which contribute to the development of IBDs, including colitis." (PMID 37233492, 2023). "Previous reports on blockade of NLRP3 with this specific NLRP3 inhibitor effectively limited the induction of DSS colitis in mice, and inhibits NF-κB, IL-1β, caspase-1 and MPO activity." (PMID 35693797, 2022). "ER stress plays a key role in human diseases, including colitis and acute pancreatitis, by increasing the release of proinflammatory factors such as IL-1β, cleaved caspase-1, and TNF-α which is elicited by TXNIP during neuroinflammation." (PMID 34790063, 2021). "In the present study, we reported for the first time that orally-administered RA-loaded niosomes markedly reduced inflammasome-related proteins such as NLRP3, ASC and caspase-1 in a DSS-induced colitis experimental model in mice." (PMID 33530569, 2021). "NLRP3 inflammasome deficiency, which comprises a deficiency of ASC, caspase-1 and NLRP3, results in a susceptibility to dextran sodium sulfate (DSS)-induced colitis, characterized by symptoms of colonic injury and enhanced inflammation." (PMID 34571825, 2021). "Following treatment with 10 mg/kg and 50 mg/kg sinapic acid, the protein levels of NLRP3, ASC, IL-1β, and caspase-1 were reduced in colitis mice." (PMID 33312339, 2020). "The colitis severity score and neutrophils infiltration showed a significant reduction in Nlrp3−/−, Pycard−/− and Casp1/11−/− mice compared to C57BL/6 mice." (PMID 32894139, 2020). "Treatment with caspase-1 inhibitors alleviated DSS-induced colitis and showed that IL-18-mediated cytokine production was an important factor in DSS-induced colitis." (PMID 33143375, 2020).